INS (insulin)
Diseases named in the same sentence as INS in open-access papers (continued):
Sharing a sentence is not in itself a finding about the gene and the disease.
diabetes (continued). "In practice, however, it occurs most frequently in patients with diabetes mellitus, usually due to over-treatment, particularly with insulin." (PMID 37892096, 2023). "Changes in IGF1 and IGFBP concentrations are, therefore, said to be associated with reduced insulin levels in the portal vein, as the therapeutic supply of insulin in diabetes comes through the subcutaneous route." (PMID 37859903, 2023). "Diabetes mellitus (DM) is a chronic metabolic condition characterized by high blood glucose levels owing to decreased insulin production or sensitivity." (PMID 37998166, 2023). "These clinicopathological scores take into consideration several variables, including age, triglycerides, diabetes mellitus, hypertension, platelet count, hyperglycemia, albumin, insulin resistance index, AST/ALT ratio, and body mass index (BMI)." (PMID 38186528, 2023). "The GLP-1 receptor agonist, such as liraglutide, promotes the synthesis and secretion of insulin, and inhibits appetite, gastric emptying and food intake to control blood glucose level in diabetes." (PMID 36777348, 2023). "Currently, oral medication and insulin therapy are some of the strategies to manage diabetes mellitus but side effects, such as low blood glucose and gastrointestinal problems, have been reported." (PMID 37755075, 2023). "Our results also indicate that diabetes treatment satisfaction is positively correlated with a positive attitude towards insulin pump therapy in general." (PMID 36801976, 2023). "Intestinal microflora can regulate the Mammalian target rapamycin (mTORC) signal pathway, thus inhibit tyrosine phosphorylation, reduce protein level, down-regulate insulin signal transduction, and exerting the effect of intestinal microorganisms on diabetes." (PMID 36673456, 2023). "Regarding the in vivo impact of insulin on autophagy, it is noted that the glycemic status, as a crucial factor, as along with insulin affect autophagy in patients with diabetes." (PMID 37876013, 2023). "Hypoglycemia and insulin-related adverse events are crucial barriers to effective diabetes management, particularly in the elderly, people with renal impairment, people with diabetes fasting during Ramadan, or people with type 1 diabetes mellitus (T1DM)." (PMID 36624651, 2023). "Being female and being on oral hypoglycaemic agent and/or insulin were the most significant predictors of poor diabetes control." (PMID 38974271, 2023). "Serum imidazole propionate, which was positively associated with species related to lower eGFR, is a microbial metabolite elevated in diabetes, shown to impair insulin signaling." (PMID 36882941, 2023). "Another important mechanism of diabetes development in OSAS patients is decreased insulin secretion, which leads to short-term or long-term hyperglycemia." (PMID 37366660, 2023). "Defect in insulin secretion is the main pathophysiological mechanism accounting for diabetes mellitus." (PMID 37289842, 2023). "Meanwhile, estrogen replacement therapy significantly improves insulin sensitivity and reduces the new onset of diabetes." (PMID 37886939, 2023). "Studies have demonstrated that the use of CGM improved glycemic control in patients with type 1 diabetes mellitus (T1DM) using daily insulin injection." (PMID 37255973, 2023). "Diabetes mellitus (DM) is a metabolic systemic multifactorial disease, where the body becomes unable to utilize or produce a sufficient amount of insulin to match the body’s needs." (PMID 38012781, 2023). "In contrast, T2DM, which makes up 90%–95% of all cases of diagnosed diabetes, is characterized by insulin resistance in conjunction with a relatively low level of insulin secretion." (PMID 37664859, 2023). "People with diabetes are always hyperglycaemic because of insulin resistance or insufficient insulin secretion." (PMID 37640738, 2023).
diabetes (continued). "Diabetes is exacerbated by overproduction of reactive oxygen species (ROS) which disrupts the insulin signaling pathway, resulting in the development of insulin resistance in diabetes." (PMID 37089941, 2023). "Diabetes patients cannot use sugar as their primary source of energy since they have poor insulin sensitivity." (PMID 37033619, 2023). "There was a statistically significant increase in the proportion of participants who correctly answered questions assessing knowledge of insulin need while fasting ( p = .01) and steroid-induced diabetes physiology ( p = .01)." (PMID 36825276, 2023). "Diabetes is a chronic metabolic condition manifesting as chronic hyperglycemia attributable to abnormal insulin secretion or insulin resistance." (PMID 37277555, 2023). "Amylin’s beneficial effects on blood glucose and weight loss led to the development of a stable amylin analogue, pramlintide, approved for use in diabetes mellitus as an adjunct to insulin." (PMID 36943057, 2023). "Although much is known about the pathogenesis and progression of the diabetes, there is still a great need to characterize novel candidates and mechanisms that regulate insulin maturation and secretion." (PMID 36939052, 2023). "For metabolic disorders, specifically in relation to diabetes, there is a great need to promote better dosage management of application and adverse effects resulting from insulin treatment." (PMID 37896204, 2023). "Despite this high prevalence, the pathophysiology of EPD in diabetes is not fully understood; until now, only the diminished nutritional effects of insulin, fibrosis and steatosis, and inflammation have been established." (PMID 37175407, 2023). "In the obesity pandemic, the emergence of insulin resistance due to the suppression of the insulin pathway is less expected and, therefore, neglected as a possible basis for diabetes and neurodegenerative diseases." (PMID 37512524, 2023). "About three quarters of the respondents on insulin regime had previous attended a diabetes class (n = 32) but just one third of the respondents on oral agents or diet regime (n = 9 vs 3) (data not shown)." (PMID 37719056, 2023). "The onset of sAD-like pathological changes in response to impaired insulin signaling induced by diabetes is a gradual process that takes a considerable amount of time to develop." (PMID 38260013, 2023). "Diabetes is a chronic disease that leads to high blood glucose levels owing to defects in insulin secretion from the pancreas, action, or both." (PMID 36607714, 2023). "Given their time to insulin was 16 years after their initial diabetes diagnosis, this suggests LADA." (PMID 37234800, 2023). "The majority of studies have shown that baicalin therapy reduced HFD-induced obesity and in that way improved insulin sensitivity and ameliorated other diabetes-related disturbances." (PMID 38203600, 2023). "Amino acids, particularly branched-chain amino acids (BCAAs), including leucine, isoleucine, and valine, are known to be increased in diabetes, influencing insulin secretion and metabolic regulation through upregulation of NADPH production." (PMID 38203517, 2023). "This review summarizes the recent development of aptasensors for the diagnosis of biomarkers of diabetes mellitus, namely glucose, insulin, HbA1c, GHSA, and ATP." (PMID 37370930, 2023). "These compounds can modulate glucose metabolism, enhance insulin sensitivity, improve lipid profiles, and exert antioxidant and anti-inflammatory effects, all of which are crucial factors in diabetes management." (PMID 37763235, 2023). "Among 106,376 patients (53.2% men; median (interquartile range) diabetes duration: 6.0 (2.0–12.0) years; mean ± SD HbA1c 8.0 ± 1.9%; 27% insulin-treated), women were older and less likely to receive college education than men (28.9% vs. 48.8%)." (PMID 36785858, 2023). "Overall, CIQ can improve outcomes for people with diabetes, and strategic insulin dose adjustments can maximize these outcomes." (PMID 37751154, 2023).
diabetes (continued). "We conducted an online survey in Italian patients with a self-reported diagnosis of diabetes to assess patient perceptions of insulin therapy management, and their impressions of connection-enabled insulin pens compared to standard insulin pens." (PMID 36828942, 2023). "In other words, not only presence of diabetes, but also diabetic condition (e.g., HbA1c level or insulin treatment) affected platelet reactivity during P2Y12 inhibitor therapy." (PMID 37679760, 2023). "Insufficient or/and low-level insulin secretion can disrupt carbohydrate and lipid metabolism in the body, finally leading to diabetes mellitus (DM)." (PMID 37444337, 2023). "Diabetes mellitus can lead to several acute consequences; one of them is hypoglycemia due to insulin use, which is a critical medical emergency seen in people with either type 1 diabetes (T1D) or type 2 diabetes (T2D)." (PMID 37859676, 2023). "Fatty acids also play a significant role, as they are involved in various metabolic processes related to diabetes, affecting insulin sensitivity and glucose metabolism." (PMID 38203517, 2023). "The results demonstrated that after adjustment for gender, diabetes duration, BMI and VFA, some associations of SFA with insulin secretion and sensitivity indices disappeared." (PMID 36909323, 2023). "Current diabetes technology includes insulin pumps; continuous glucose monitoring devices (CGM); and automated insulin delivery systems (AID) that combine the pump and CGM functions through an algorithm that can assist with regulating glucose levels." (PMID 37522857, 2023). "Roseburia species can restore insulin sensitivity and alleviate diabetes mellitus; moreover, they can promote the differentiation of regulatory T cells and induce transforming growth factor-β-based suppression of intestinal inflammation." (PMID 37065128, 2023). "Exosomes isolated from diabetic cardiomyocytes and insulin resistant adipocytes inhibit angiogenesis, demonstrating that the presence of diabetes can alter the content of exosomes." (PMID 37179303, 2023). "As an adipocytokine secreted by and sensed by adipocytes, apelin is necessary for the maintenance of insulin sensitivity and tends to counteract diabetes mellitus." (PMID 36982812, 2023). "Diabetes mellitus is a diverse metabolic disorder featured by the incidence of hyperglycemia based on diminishing of insulin secretion, defective insulin action, or both." (PMID 36932309, 2023). "Trying to appear as “normal” is a major focus of adolescents with CPHC, potentially leading to more negative illness cognitions, especially in conditions with physical manifestations of the illness (i.e., insulin pumps in diabetes)." (PMID 36902714, 2023). "We adjusted the model for diabetes, prevalent cardiovascular disorders, socioeconomic status, diet, alcohol consumption, physical activity, medication intake (insulin, biguanides, statins and aspirin), and baseline characteristics." (PMID 37538264, 2023). "Despite the measures implemented in 2010 by the National Patient Safety Agency (NPSA) in the United Kingdom to reduce insulin prescription errors, the National Diabetes Inpatient Audit has revealed high levels of errors associated with insulin prescriptions." (PMID 37719599, 2023). "Regular exercise is recommended for diabetes management, as physical activity increases insulin sensitivity and thus is critical for improving blood glucose control." (PMID 36724895, 2023). "The most common forms of diabetes result from the body’s inability to produce insulin in pancreatic beta cells (type 1 diabetes) or to respond to insulin (type 2 diabetes)." (PMID 38229904, 2023). "Body is unable to synthesize sufficient insulin in case of type 1 diabetes mellitus while type 2 diabetes mellitus has a characteristics of development of resistance for insulin hitting and this insulin dependency aspect is temporary." (PMID 37193696, 2023).
diabetes (continued). "Diabetes mellitus is defined as “a chronic disease that occurs either when the pancreas does not produce enough insulin or when the body cannot effectively use the insulin that is produced”." (PMID 36875280, 2023). "Some anti-diabetic drugs were already found to influence this process but for one of the major treatments of diabetes, insulin, nothing is known so far." (PMID 37626968, 2023). "In particular, the regulation of insulin secretion by islet β cells has been considered a target for diabetes treatment." (PMID 36398677, 2023). "In this study, the D and SD groups had higher levels of diabetes-related factors (insulin, HOMA-IR, TyG Index, FPG, and HbA1c) and obesity-related factors (triglycerides, waist circumference, BMI, and fat mass) than did the S group." (PMID 38068813, 2023). "Hypometabolism is often accelerated in the context of insulin resistance which destabilizes the brain network, triggering diabetes-induced dementia." (PMID 36984824, 2023). "The difference in A1C reduction between the three groups remained statistically significant after adjusting for age, sex, diabetes type, diabetes duration, and percentage of participants treated with insulin (p < 0.001)." (PMID 37194402, 2023). "Diabetes mellitus (DM) is a worldwide-prevalent chronic disease inherited from natural or acquired insufficiencies and ineffectiveness of insulin secretion." (PMID 36908916, 2023). "T2DM, accounting for approximately 90% of diabetes cases, arises from insulin-resistant cells requiring elevated insulin levels for effective sugar metabolism." (PMID 38201117, 2023). "While the primary focus of insulin administration has historically centered on its role in the treatment and management of diabetes, its potential therapeutic effects in other fields have also been a subject of investigation." (PMID 38276493, 2023). "Type 1 diabetes mellitus (T1DM) is characterized by insufficient insulin production that is mainly attributed to the gradual destruction of pancreatic β-cells triggered by an autoimmune response." (PMID 37859703, 2023). "Anti‐insulin antibodies in insulin‐treated diabetes can derange glycaemia, but are under‐recognised." (PMID 37562398, 2023). "Studies have also reported that these mediators influence the progression of type 2 diabetes mellitus directly by taking part in the insulin resistance pathway mechanism." (PMID 37809241, 2023). "Diabetes mellitus (DM) is a group of metabolic disorder characterized by an elevated blood glucose level as a result of limitation in insulin secretion or an inability to use insulin." (PMID 37964349, 2023). "Among these, 10,766 (45.7%) were prescribed diabetes drugs at baseline out of which 380 (3.5%) were on insulin and 8489 (78.8%) were on metformin." (PMID 37563596, 2023). "For example, contrast-enhanced ultrasound (CEUS) perfusion imaging has been used to evaluate skeletal muscle perfusion (poor in diabetes) in diabetes by measuring microvascular blood volume and capillary responsiveness to insulin." (PMID 37754812, 2023). "Detailed perinatal care is required for women with preexisting diabetes; this care includes frequent blood glucose monitoring, insulin injections, and evaluation of microvascular complications." (PMID 37828526, 2023). "Treatment of murine models of diabetes mellitus (DM) improved insulin release and glucose tolerance." (PMID 36647824, 2023). "Diabetes patients often experience frustration when they become aware of their condition and start taking medication, particularly insulin." (PMID 37893847, 2023). "At the same time, these findings are important considering the current clinical trials exploring the use of dual insulin/glucagon pumps for the treatment of diabetes." (PMID 37140984, 2023). "Diabetes mellitus (DM) is a chronic disease resulting from the impaired production or inadequate effects of insulin." (PMID 36766785, 2023).
diabetes (continued). "We believe that further unveiling the mechanisms that regulate GLUT4 gene expression in diabetes will hopefully result in finding effective ways to improve overall insulin sensitivity in epileptic populations." (PMID 37334286, 2023). "An in vivo experimental study demonstrated that 100% of LAG3 knockout mice develop diabetes with a peak insulin level, suggesting rapid destruction of pancreatic β cells." (PMID 37880788, 2023). "In the reviewed studies, 80% suggested dietary modification for diabetes, insulin therapy, or exercise for people with diabetes." (PMID 37276013, 2023). "Previous research indicates that those with a family history of diabetes have impaired insulin sensitivity at an early age, and first‐degree relatives of patients with EOT2D are more likely to develop diabetes." (PMID 37750029, 2023). "The study was also retrospective and had variability between the study groups at baseline, such as differences in percentage of participants with T1D, diabetes duration, systolic BP, diastolic BP, and percentage of participants treated with insulin." (PMID 37194402, 2023). "Doses in range of 25 and 100 mg/kg can cause varying severity of diabetes caused by increased doses of STZ, characterized by an increase in serum glucose levels and a progressive decrease in insulin levels at 24 h." (PMID 37990213, 2023). "Die vorliegende Leitlinie nimmt Bezug auf die Indikation und praktische Umsetzung der Injektionstherapie (GLP1-Rezeptor Agonisten und Insulin) bei Typ 2 Diabetes." (PMID 37101024, 2023). "Type 2 diabetes mellitus occurs due to impaired insulin secretion from the β-pancreatic cells or due to insulin resistance in which cells don’t respond to the secreted insulin." (PMID 37147652, 2023). "Defects in insulin secretion can lead to diabetes, underscoring the importance of understanding the complex mechanisms that regulate this critical process." (PMID 38027137, 2023). "Type 1 diabetes mellitus induced by them (ICI-T1DM) is a serious complication requiring prompt insulin treatment, but the immunological mechanism behind it is unclear." (PMID 37114039, 2023). "The α-glucosidase inhibitors effectively compensate for insufficient insulin secretion in insulin-dependent diabetes mellitus by binding to the enzyme and interfering with the dissolution and absorption of monosaccharides (i.e., glucose)." (PMID 37763199, 2023). "Type 2 diabetes mellitus (T2DM) is a chronic disease motivated by the body’s ineffective use of insulin." (PMID 37511996, 2023). "Continuous Insulin Subcutaneous Therapy (CSII) is widely used in the pediatric population with diabetes; however, it requires more preparation by the treating team and a careful selection of its potential users." (PMID 37232708, 2023). "TUDCA was previously employed by other researchers to restore insulin homeostasis through improving the adaptive UPR response of the β-cell in various diabetes models." (PMID 36768343, 2023). "For the GDS3875 dataset, which is another study on Diabetes, PriPath’s top predictions are Herpes simplex virus 1 infection (hsa05168), Insulin signaling pathway (hsa04910), and pathways of neurodegeneration—multiple diseases (hsa05022)." (PMID 36823571, 2023). "A retrospective cohort study was carried out in patients with diabetes previously treated with an intensive insulin regimen at a specialized diabetes treatment center who required a sensor-augmented insulin pump due to nonoptimal glycemic control." (PMID 37610810, 2023). "In the UK, there are ~ 4.7 million people with diabetes, 90% have T2D, and approximately 30–40% with T2D are either prescribed or require insulin." (PMID 37237318, 2023). "This PICK1-activated pathway increases GLUT2 expression and functionally protects pancreatic β cells, promoting insulin secretion and slowing the progression of type 2 diabetes mellitus." (PMID 37123284, 2023).